Y_RNA (Y RNA )
Gene: Miscellaneous RNA gene on chromosome 11 (64,296,037 to 64,296,138, forward strand). Ensembl gene ENSG00000207024.
Homologues: Orthologues: chimpanzee Y_RNA (99% identical). Paralogues in human: RNY3 (93% identical), Y_RNA (92% identical), Y_RNA (91% identical), RNY3P1 (90% identical), Y_RNA (90% identical), Y_RNA (89% identical), Y_RNA (88% identical), RNY3P14 (87% identical), Y_RNA (87% identical), RNY3P16 (86% identical), RNY3P4 (86% identical), RNY3P5 (86% identical), and 96 more.